ATR (ATR checkpoint kinase)
Diseases named in the same sentence as ATR in open-access papers (continued):
Sharing a sentence is not in itself a finding about the gene and the disease.
pancreatic cancer (continued). "Overall, our observations suggest that APE2 regulates the ATR DDR pathway in response to different stressful conditions in human pancreatic cancer cells." (PMID 34796173, 2021). "This study provides evidence using pancreatic cancer cell lines that activation of the ATR-Chk1 DDR pathway induced by hydrogen peroxide (H2O2), GEM, CPT, and ETO is compromised when APE2 is down-regulated via siRNA." (PMID 34796173, 2021). "For example, in HR-proficient xenograft models of pancreatic cancer, the combination of ATR inhibition, PARPi and radiation results in synergistic anti-tumor activity." (PMID 34572943, 2021). "A combination of GEM with radiotherapy or other chemotherapy drugs such as ATR inhibitor AZD6738 shows great promise in pancreatic cancer regression." (PMID 34796173, 2021). "Here, we provide evidence using human pancreatic cancer cells that APE2 is essential for ATR DDR pathway activation in response to different stressful conditions including oxidative stress, DNA replication stress, and DNA double-strand breaks." (PMID 34796173, 2021). "Consistently, human and murine BAP1-deficient pancreatic cancer cell lines showed a pronounced sensitivity and activation of ATM/ATR kinases and H2A.XSer139 phosphorylation upon different means of DNA damage." (PMID 32541668, 2020). "Significant progress has been made in enhancing effectiveness of chemotherapeutic agents by targeting ATR-Chk1 pathway in many cancer cells, such as colorectal cancer, pancreatic cancer, human osteosarcoma." (PMID 27246979, 2016). "A close analogue of VE-821, named VE-822 (or alternatively CX970), with even increased potency against ATR was shown to radiosensitize and chemosensitize pancreatic cancer cells in vitro and pancreatic tumor xenografts in vivo." (PMID 26295265, 2015). "Several of these gene targets such as STK6 and ATR have previously been studied as therapeutic targets in pancreatic cancer." (PMID 19519883, 2009). "Epigenetic silencing of FAM110C sensitized pancreatic cancer cells to ATR/CHK1 inhibitors." (PMID 39081276, 2024). "Therefore, the colorectal cancer cell line HCT-116 and the pancreatic cancer cell line PaTu8988t were treated with ATR and CHK1 inhibitors, respectively." (PMID 39128273, 2024). "In another study with pancreatic cancer cells treated with gemcitabine in combination with ATR inhibitor ceralasertib (AZD6738), pharmacologic inhibition with the ATM inhibitor AZD0156 or knockout through CRISP-R of ATM led to replication catastrophe and cell death." (PMID 36975505, 2023). "The third line of evidence of APE2’s role in ATR DDR was shown in pancreatic cancer cells." (PMID 36755963, 2023). "To determine the role of APE2 in the ATR DDR pathway in pancreatic cancer cells, we first established that H2O2 triggered Chk1 and RPA32 phosphorylation in human pancreatic cancer PANC1 cells and that ATR-specific inhibitor VE-822 prevented H2O2-induced Chk1 and RPA32 phosphorylation." (PMID 34796173, 2021). "Our finding in this study on the critical role of APE2 in the ATR DDR pathway in pancreatic cancer cells provides vital knowledge for future translational studies targeting APE2 functions in various mice models with different genetic backgrounds such as deficiency of ATM or BRCA1/2." (PMID 34796173, 2021). "Next, we tested whether Celastrol affects the ATR-Chk1 DDR pathway in human pancreatic cancer cells." (PMID 34796173, 2021). "We therefore examined whether the combination of olaparib plus an ATR inhibitor would be effective in cell line models of prostate and pancreatic cancer." (PMID 32183301, 2020).
pancreatic cancer (continued). "The ATR inhibitor VE-821 has been shown to significantly enhance the sensitivity of pancreatic cancer cells to radiation and gemcitabine, to enhance the sensitivity of ovarian cell lines to cisplatin, topotecan, and veliparib, and to radiosensitize human promyelocyte leukaemia cells." (PMID 27472395, 2016). "Notably, Celastrol treatment impairs the ATR-Chk1 DDR pathway in pancreatic cancer cells." (PMID 34796173, 2021). "Little is known about the role of APE2 in ATR activation under unperturbed conditions, however APE2 is a critical upstream regulator of ATR activation from SSB in Xenopus egg extracts and in pancreatic cancer cells." (PMID 36755963, 2023). "In a case series on pancreatic ductal adenocarcinoma, 8 out of 10 pancreatic cancer patients with ATM, ATR, or CHEK2 GPVs were treated with an oxaliplatin-based chemotherapy regimen and 5 patients demonstrated a partial response or stable disease." (PMID 35806485, 2022). "To exclude the possible cell-specific role of APE2 in the ATR DDR pathway, we performed similar experiments in another human pancreatic cancer MiaPaCa2 cells and found that APE2 was also important for the H2O2-induced ATR-Chk1 DDR pathway in MiaPaCa2 cells." (PMID 34796173, 2021). "Our findings on APE2 in the ATR-Chk1 DDR pathway in both the Xenopus system and pancreatic cancer cells prompt us to target the function and regulatory mechanism of APE2 in the ATR DDR pathway for cancer therapy." (PMID 34796173, 2021). "This study demonstrated that APE2 is important for the ATR-Chk1 DDR pathway in response to different stress conditions including oxidative stress, DNA replication stress, and DSBs in pancreatic cancer cells." (PMID 34796173, 2021). "Our observations in this study support the important role of APE2 in the ATR-Chk1 DDR pathway in response to hydrogen peroxide-induced oxidative stress, GEM-induced DNA replication stress and CPT/ETO-induced DSBs in human pancreatic cancer cell." (PMID 34796173, 2021). "The impairment of ATR-Chk1 DDR pathway by Celastrol in Xenopus egg extracts and human pancreatic cancer cells highlights the physiological significance of Celastrol in the regulation of APE2 functionalities in genome integrity." (PMID 34796173, 2021). "Deletion of ATM in mouse models of lung cancer and pancreatic cancer also induced sensitivity to PARP inhibitors and/or DNA damaging agents, as did inhibitors of the related protein kinase ATR (ATM and Rad3-related)." (PMID 32183301, 2020). "The inhibitions of some DDR molecules, such as CHK1 (checkpoint kinase 1) and ATR, have been demonstrated to enhance the effect of GEM in resistant pancreatic cancers." (PMID 33182492, 2020). "Proteins downstream of ATM, chiefly ATR and CHK1/2, are also potential targets for therapy in patients with pancreatic cancer." (PMID 31963441, 2020). "A recent report showed that VE-821, a novel ATR inhibitor, increased sensitivity to low LET radiation in pancreatic cancer cells." (PMID 26286029, 2015). "To explore the mechanism by which VPA upregulates MICA and MICB in pancreatic cancer cells, we examined the expression and activation of components of the HER2/HER3, ATM/ATR, and PI3K/Akt pathways." (PMID 24885711, 2014).
pancreatic cancer (continued). "WEE1 inhibitors may also be synergistic with nucleoside analogue chemotherapy drugs, such as gemcitabine, by reducing the ATR and CHK1 activation induced by gemcitabine exposure of pancreatic cancer cells." (PMID 36975505, 2023). "In pancreatic cancer, BRD4770 induced senescent phenotype and activated the ATM (ataxia telangiectasia mutated) pathway to induce DNA damage without affecting ATR (ATM- and Rad3-related) pathway, which ultimately restrained the cell growth." (PMID 37306883, 2023). "Nevertheless, a systematic examination of ATR inhibitors and combinations with chemotherapy or PARP inhibitors specifically in pancreatic cancer patients with ATM mutations has not been performed and needs to be investigated prospectively in a clinical trial." (PMID 36975505, 2023). "Several radiosensitizers have been clinically studied in a variety of malignancies, including CHK1/CHK2 inhibitors, ATM/ATR inhibitors, and PARP inhibitors, but clinical trials of pancreatic cancer-related radiosensitizers are still relatively scarce and most are in the preclinical stage." (PMID 35053488, 2022). "Notably, the ATR-Chk1 DDR pathway activation induced by H2O2, GEM, CPT, and ETO in pancreatic cancer cells was compromised by the addition of Celastrol." (PMID 34796173, 2021). "Our evidence suggests that APE2 regulates the ATR DDR pathway in pancreatic cancer cells and that targeting the novel function of APE2 in ATR DDR may open a new avenue for future therapeutics in pancreatic cancers." (PMID 34796173, 2021). "Even though a number of ATR and CHK1 inhibitors have been developed and tested as potential anti-tumor agents, the efforts are mainly focused on tumor types exhibiting high levels of replication stress, such as melanoma, pancreatic cancer, and neuroblastoma." (PMID 34663432, 2021). "Possible synthetic lethal interactions may be produced in patients with pancreatic cancer using the new targeted therapies, ATM or ATR inhibitors, as ATM and ATR are key participants in DNA repair." (PMID 29069866, 2017). "Interestingly, PRRX1 could transcriptionally maintain the expressions of DDR genes including ATM, ATR, BRCA1, PRKDC, and XRCC1, in PANC1 pancreatic cancer cells." (PMID 40114375, 2025). "While the PARP inhibitor talazoparib in combination with enzalutamide is FDA approved for the treatment of select patients with ATR-mutant metastatic castration-resistant prostate cancer, no ATR-targeted therapy for pancreatic cancer was identified in the OncoKB database." (PMID 38542259, 2024). "siRNA-mediated knockout of APE2 has been shown to eliminate ATR/Chk1 DDR in response to genotoxic stress in pancreatic cancer cells, indicating that APE2 may be highly regulated and differentially activated only under certain conditions to control ATR/Chk1 DDR." (PMID 36755963, 2023). "Previous studies show that ATR inhibitor VE-822 sensitizes cancer cells to radiation or chemotherapy drugs such as CPT, and that Chk1-KD by siRNA or Chk1 inhibition by small molecule inhibitor AZD7762 has been shown to function in a synthetically lethal manner with GEM in pancreatic cancers." (PMID 34796173, 2021).
melanoma (45 papers, 2014 to 2026). A malignant, usually aggressive tumor composed of atypical, neoplastic melanocytes. "Loss-of-function mutations have been reported in ATR in a subset of melanomas where about 7% of melanoma tumors in the TCGA have mutations in genes that affect the ATR pathway." (PMID 40940791, 2025). "ATR mutation can regulate the tumor immune microenvironment in melanoma models and promote tumor growth." (PMID 36071479, 2022). "In melanoma, ATR mutation is related to inhibitory TME features such as increased inhibitory macrophages." (PMID 36071479, 2022). "Homozygous ATR mutated melanomas showed a reduction in the number of infiltrating CD3+ T cells, but an increase in the infiltrating macrophages and B cells, compared to ATR wt or hemizygous mutated tumors." (PMID 35563772, 2022). "Recently, a work from Chen and colleagues showed that ATR mutations modulate the tumor immune microenvironment in melanoma models, leading the immune system to accelerate tumor growth." (PMID 35563772, 2022). "We compared ATR protein levels in the SPR-proficient vs -deficient melanoma strains by Western blotting." (PMID 24416382, 2014). "Our data suggest that defective NER exclusively during S phase, possibly associated with decreased ATR signaling, may constitute an heretofore unrecognized determinant in melanoma pathogenesis." (PMID 24416382, 2014). "In addition, ATR mutation of the melanoma can induce the accumulation of M2 TAMs and promote tumor proliferation, indicating that ATR mutation may be related to the polarization of M2 TAMs18." (PMID 32917854, 2020). "In BL6-10 melanoma cells, reduced expression of ATR, ATM, and CDK1/2 during the transition from the S-phase to the G2-phase has been observed under microgravity conditions, which corresponds with a notable decline in the population of G2-phase cells." (PMID 41513600, 2026). "The results showed that melanoma cell lines responded to the cytotoxic effect of the ATR inhibitor itself." (PMID 39594759, 2024). "In contrast, the ATR inhibitor (ATRi) VE-822 led to additive enhancement of IR-related toxicity in most of the melanoma cells." (PMID 36229655, 2023). "A promising anticancer activity was also revealed in a phase 2 trial of melanoma patients treated with the combination of ATR inhibitor ceralasertib with durvalumab." (PMID 36831197, 2023). "The major evidence attributing a therapeutic value in melanoma to ATR inhibitors comes from recent clinical trial results." (PMID 35563772, 2022). "Recent clinical trials have confirmed that ceralasertib, an oral ATR inhibitor, combined with durvalumab/paclitaxel is effective in advanced melanoma (including AM) [204•, 205]." (PMID 36125617, 2022). "Taken together, these data pointed to the emerging role of ATR in the tumor immune microenvironment and suggested a significant benefit of using ATR inhibitors, in combination with immunotherapy, in melanoma." (PMID 35563772, 2022). "In A431 melanoma cells, Stat3 decreased the expression of miR-383 and, as the direct target of miR-383, ATR expression was increased." (PMID 34976192, 2022). "Another recent analysis of human melanoma found that 21.4% of this tumor type has at least one HRD gene mutation including BRCA1, ARID1A, ATM, ATR and FANCA." (PMID 34885093, 2021). "This increased DNA damage confers synergism with an ATR inhibitor in both glioma and melanoma cells." (PMID 30863489, 2019). "Further, 3E10 was found to synergize with a small molecule inhibitor of the ataxia telangiectasia and Rad3-related (ATR) protein, a DNA damage checkpoint kinase, in both PTEN-deficient glioma cells and primary melanoma cells." (PMID 30863489, 2019).
melanoma (continued). "Western blot analysis showed that both compounds increased DNA damage in melanoma cells by inducing phosphorylation of ATR and consequently activation of the downstream target pCHK1." (PMID 29396391, 2018). "Concomitant inhibition of BET proteins and ATR of cultured melanoma cells resulted in similar effects as recently shown in lymphoma, such as induction of apoptosis and p62, implicated in autophagy, senescence-associated secretory pathway and ER stress." (PMID 28796244, 2017). "We initially treated the three SPR-proficient melanoma strains in our collection with (i) 10 mM caffeine known to inhibit both ATR and ATM, or (ii) 30 μM wortmannin which inhibits ATM and DNA-PK but not ATR followed by exposure to IR or UV." (PMID 24416382, 2014). "The interdependency of Notch1 and ATR/ChK1 pathways and the sensitivity of melanoma cells to their concurrent inhibition, is comparable to the synthetic lethal interactions observed for example in BRCA mutated tumor cells and PARP (poly (ADP-ribose) polymerase) inhibitors (PARPi)." (PMID 40437523, 2025). "Clinical trials, such as those involving ceralasertib, have demonstrated encouraging results, particularly in melanomas resistant to PD-1 inhibitors, suggesting the value of ATR inhibitors in enhancing immune responses and improving outcomes in melanoma treatment." (PMID 38474231, 2024). "Moreover, pathways such as the DNA damage response and cell proliferation pathways have been reported to be associated with the genome instability of melanoma, and mutations, including ATM and ATR, have been reported in some melanomas." (PMID 39039072, 2024). "In addition, a high level of A3B conferred sensitivity to ATR/Chk1 inhibitors (ATRi/Chk1i) in melanoma cells, which was dependent on R-loop status." (PMID 37270643, 2023). "Others have shown that combination inhibition of BRD4 and ATR demonstrates synergistic cytotoxic activity in other cancers such as lymphomas, melanoma and high-grade serous ovarian cancer 58–60, however ARID1A loss as a biomarker of sensitivity was not explored." (PMID 37841875, 2023). "In this paper, we will depict the current evidence on the effect of PARP, ATM, CHK1, WEE1 and ATR inhibitors both in preclinical and clinical settings in melanoma, both as monotherapy and in combination with other targets belonging to the pathways crucial for melanoma proliferation and survival." (PMID 35563772, 2022). "The molecular mechanism of SL-mediated G2/M arrest and apoptosis in melanoma cell lines suggests that SLs are possible alkylating agents that might cause DNA damage, which activates the kinase ATM/ATR." (PMID 36359261, 2022). "Studies have also reported that ATR was a target for miR-383 in canine malignant melanoma, indicating that miR-383 may be involved in melanoma tumorigenesis by inhibiting DNA repair or apoptosis." (PMID 34976192, 2022). "It is conceivable that melanoma, characterized by high levels of replication stress, may be highly responsive to ATR inhibitors." (PMID 35563772, 2022). "Inhibition of ATR is also shown to strongly synergise with these low doses of gemcitabine, whereas we found that only higher concentrations (> 1 mm) of HU sensitised melanoma TSs to ATR inhibition." (PMID 31044505, 2019). "In this respect, it is noteworthy that large-scale whole-exome sequencing studies have not revealed mutations within the ATR coding region in primary melanomas." (PMID 24416382, 2014). "Interestingly one recent report showed that the CDC42 homologue RhoJ and its effector PAK1 modulate ATR activity via degradation of claspin after DNA damage thereby uncoupling ATR from Chk1; moreover RhoJ appears to be upregulated in advanced melanoma." (PMID 24416382, 2014). "However we show here that one among the eleven SPR-deficient melanoma strains, i.e., WM3248, display greatly reduced ATR protein levels compared with SPR proficient counterparts." (PMID 24416382, 2014).